RNU7-2P (RNA, U7 small nuclear 2 pseudogene)
Synonyms: U7.2
Gene: Small nuclear RNA gene on chromosome 2 (146,145,156 to 146,145,217, forward strand). Ensembl gene ENSG00000251905.
Homologues: Orthologues: chimpanzee U7 (100% identical), macaque U7 (94% identical). Paralogues in human: RNU7-1 (92% identical), RNU7-10P (90% identical), RNU7-11P (90% identical), RNU7-25P (90% identical), RNU7-41P (90% identical), RNU7-8P (90% identical), RNU7-9P (90% identical), RNU7-13P (89% identical), RNU7-18P (89% identical), RNU7-26P (89% identical), RNU7-3P (89% identical), RNU7-43P (89% identical), and 143 more.